CEACAM8 (CEA cell adhesion molecule 8)
Description:
Cell surface glycoprotein that plays a role in cell adhesion in a calcium-independent manner. Mediates heterophilic cell adhesion with other carcinoembryonic antigen-related cell adhesion molecules, such as CEACAM6. Heterophilic interaction with CEACAM8 occurs in activated neutrophils.
Synonyms: CD66b; CGM6; CD67; NCA-95
Tractability: Antibody: UniProt places it where antibodies can reach, with high confidence; its Gene Ontology location is reachable by antibodies, with high confidence; UniProt predicts a signal peptide or a membrane-spanning region.
Gene: Protein-coding gene on chromosome 19 (42,580,243 to 42,595,055, reverse strand). Ensembl gene ENSG00000124469.
Subcellular location: Cell membrane; Cell surface
Pathways (Reactome):
Extracellular matrix organization: Fibronectin matrix formation
Hemostasis: Cell surface interactions at the vascular wall
Immune System: Neutrophil degranulation
Gene Ontology:
Molecular function: protein binding; protein heterodimerization activity
Biological process: heterophilic cell-cell adhesion; homophilic cell-cell adhesion; immune response
Cellular component: cell surface; extracellular exosome; extracellular region; plasma membrane; azurophil granule membrane; specific granule membrane; tertiary granule membrane
Genetic constraint (gnomAD): Loss-of-function variants: 29 observed, 32.43 expected, observed/expected ratio (o/e) 0.89, 90% interval 0.67 to 1.22. The upper end of that interval is the gene's LOEUF score, 1.22, which puts it in group 5 of 6, group 1 being the genes least tolerant of losing a copy. Missense variants: 360 observed, 416.42 expected, observed/expected ratio (o/e) 0.86, 90% interval 0.79 to 0.94. Synonymous variants: 126 observed, 159.12 expected, observed/expected ratio (o/e) 0.79, 90% interval 0.68 to 0.92.
Homologues: Orthologues: chimpanzee CEACAM8 (99% identical), macaque CEACAM8 (89% identical). Paralogues in human: CEACAM6 (77% identical), CEACAM1 (77% identical), CEACAM5 (75% identical), CEACAM7 (51% identical), PSG8 (46% identical), PSG1 (45% identical), PSG7 (45% identical), PSG9 (44% identical), PSG6 (44% identical), PSG3 (44% identical), PSG4 (44% identical), PSG2 (40% identical), and 12 more.